RNU6-509P (RNA, U6 small nuclear 509, pseudogene)
Gene: Small nuclear RNA gene on chromosome 3 (141,902,924 to 141,903,030, reverse strand). Ensembl gene ENSG00000200389.
Homologues: Orthologues: guinea pig U6 (81% identical). Paralogues in human: RNU6-820P (93% identical), RNU6-11P (91% identical), RNU6-37P (91% identical), RNU6-45P (91% identical), RNU6-12P (90% identical), RNU6-13P (90% identical), RNU6-16P (90% identical), RNU6-25P (90% identical), RNU6-26P (90% identical), RNU6-31P (90% identical), RNU6-32P (90% identical), RNU6-41P (90% identical), and 1286 more.